HOTAIR (HOX transcript antisense RNA)
Diseases named in the same sentence as HOTAIR in open-access papers (continued):
Sharing a sentence is not in itself a finding about the gene and the disease.
gastric cancer (continued). "The average percentage of tumors with increased HOTAIR expression was 42.0%, with a maximum of 67.5% in gastric cancer and a minimum of 13.7% in pancreatic cancer." (PMID 25157956, 2014). "The results demonstrated that HOTAIR was upregulated in gastric carcinoma tissues in comparison with adjacent normal gastric tissues, and that HOTAIR upregulation correlated with larger tumor size, advanced pathological stage and extensive metastasis." (PMID 24775712, 2014). "In this study, we investigated the expression of HOTAIR in gastric cancer and examine its correlation with the clinicopathological features including patients’ prognosis." (PMID 24130837, 2013). "We examined the expression of HOTAIR in 68 gastric cancer samples using quantitative real-time RT-PCR and analyzed its correlation with the clinical parameters." (PMID 24130837, 2013). "To elucidate the functions of HOTAIR in the anchorage-independent growth of gastric cancer cells, we utilized a soft agar assay." (PMID 24130837, 2013). "The functional role of HOTAIR was examined by generating human gastric cancer cell lines with increased or suppressed HOTAIR expression." (PMID 24130837, 2013). "To assess the functional role of HOTAIR in gastric cancer development, we generated stably HOTAIR expressing MKN74 cells (MKN-HOTAIR) and stably shHOTAIR expressing KATO III cells (KATO-shHOTAIR)." (PMID 24130837, 2013). "In gastric cancer tissues, specific lncRNAs, such as HOTAIR, exhibit significant expression differences, and these differentially expressed lncRNAs may serve as potential prognostic indicators and therapeutic targets for gastric cancer." (PMID 40282384, 2025). "Similarly, HOTAIR was recently reported to modulate the Wnt/β-Catenin signaling pathways in gastric cancer by sponging miR-34a." (PMID 39519092, 2024). "HOTAIR, a frequently overexpressed lncRNA, may contribute to the dissemination of gastric-cancer cells." (PMID 38542354, 2024). "Furthermore, HOTAIR modulates the activation of both signaling pathways in the context of cisplatin resistance by down-regulating miR-34a in gastric cancer." (PMID 39273054, 2024). "Similarly, in gastric cancer, upregulation of HOTAIR has been found to suppress the expression of miR‐130a, leading to enhanced cancer cell proliferation and metastasis." (PMID 39347925, 2024). "HOTAIR enhances EMT by affecting the miR-17-5p/PTEN axis in gastric cancer." (PMID 37576402, 2023). "Moreover, again in gastric cancer, the regulatory role of HOTAIR in promoting EMT was ascribed to the regulation of miR-217 that, in turn, impairs the levels of the GPC5 protein, correlated to proliferation and invasion." (PMID 37308974, 2023). "Interestingly, in gastric cancer HOTAIR directly binds and induces degradation of miR-30a and −30b and this results in the regulation of both cellular and exosomal expression of these miRNAs." (PMID 37308974, 2023). "Similarly in gastric cancer cells, by means of the interaction with Mex3b, HOTAIR can induce the ubiquitination, and subsequent degradation, of Runx3, thus enhancing cell invasion capacity." (PMID 37308974, 2023). "A previous study reported that HOTAIR was the target of miR-331-3p, and HER2 was the target of miR-331-3p through a luciferase assay, which suggested that lncRNA HOTAIR could regulate HER2 expression by sponging miR-331-3p in gastric cancer." (PMID 35168607, 2022). "Moreover, HULC, H19, HOTAIR and GACAT2 (for “gastric cancer-associated transcript 2”) were found to be significantly increased in the plasma of gastric cancer (GC) patients compared to healthy individuals." (PMID 35729321, 2022). "Therefore, the interaction between HOTAIR and Mex3b can induce the ubiquitination of Runx3 protein and enhance the invasion ability of gastric cancer cells, and providing a potential therapeutic target for gastric cancer metastasis." (PMID 35813070, 2022).
gastric cancer (continued). "Furthermore, the PI3K/AKT signaling pathway was found to be involved in HOTAIR-mediated cell apoptosis and chemotherapy resistance in BC and gastric cancer (GC)." (PMID 36100611, 2022). "Corresponding results demonstrated that HOTAIR silencing could effectively inhibit gastric cancer cell proliferation, invasion, and migration and promote apoptosis by retaining cells in G1 phase." (PMID 33473276, 2021). "For example, lncRNA HOTAIR, as a competitive endogenous RNA, effectively acts as a sink of miR-331-3p, thus modulating hairy-related 2 inhibition and its expression is positively correlated with gastric cancer progression." (PMID 34696660, 2021). "The HOTAIR mRNA expression of SGC‐7901 cell line was highest in gastric cancer cell lines." (PMID 33473276, 2021). "For example, HOTAIR could competitively bind miR-331-3p to regulate the HER2 expression in gastric cancer." (PMID 33294032, 2020). "In a study on gastric cancer, HOTAIR could indirectly regulate the expression of HER2 by binding to miR-331-3p." (PMID 33102210, 2020). "Mechanistically, HOTAIR blocks the miR-331-3p-mediated downregulation of HER2 in gastric cancer." (PMID 33291485, 2020). "Previous studies revealed that HOTAIR overexpression could predict unfavorable outcome in gastric cancer." (PMID 32104724, 2020). "HOTAIR regulates HER2 expression by sponging miR-331-3p in gastric cancer." (PMID 32349783, 2020). "High HOTAIR expression was also used as a predictor of poor OS in gastric cancer (GC), and inhibition of HOTAIR could reduce invasiveness and reverse epithelial-mesenchymal transition (EMT) in GC cells." (PMID 32104724, 2020). "Though a growing number of long noncoding RNAs (lncRNAs), including HOTAIR, MEG3, MALAT1, H19, GAPLINC, and GClnc1, have been reported to be associated with gastric cancer tumorigenesis, the role of lncRNAs in human gastric cancer and their prognostic value are still inadequately explored." (PMID 32117443, 2020). "Interestingly, HOTAIR expression was positively correlated with miR‐17‐5p expression among the 317 gastric cancer patients investigated (rs = 0.49; P < 0.05)." (PMID 30338929, 2019). "HOTAIR and gastric cancer are the most studied lncRNA and disease, respectively." (PMID 30759219, 2019). "Furthermore, both higher HOTAIR and miR‐17‐5p expressions were discovered within gastric cancer patients who were poorly differentiated and at advanced AJCC stages (ie III+IV) (P < 0.05)." (PMID 30338929, 2019). "In summary, this research initially interpreted the inhibitory effects of HOTAIR/miR‐17‐5p/PTEN axis on chemosensitivity of gastric cancer cells, and drawn a conclusion that SQFZ injection could reverse this impact." (PMID 30338929, 2019). "HOTAIR up-regulation has been suggested as a result of rs920778 in gastric cancer." (PMID 30873206, 2019). "This study was implemented to figure out whether lncRNA HOTAIR/miR‐17‐5p/PTEN axis played a role that was opposite to Shenqifuzheng (SQFZ) injection in regulating the chemosensitivity of gastric cancer cells." (PMID 30338929, 2019). "In a meta-analysis showed that HOTAIR rs4759314 polymorphism was a risk factor only for gastric cancer, but not for lung, breast, colorectal, and esophageal cancer in Chinese populations." (PMID 30813594, 2019). "In addition, the lncRNA HOTAIR is overexpressed in gastric cancer and either promotes cell proliferation and metastasis by functioning as a ceRNA to sponge up miR-331-3p or epigenetically silences miR34a by binding to PRC2." (PMID 27713133, 2017). "We previously reported that HOTAIR can regulate invasion and cell proliferation in gastric cancer." (PMID 28077118, 2017). "In addition, HOTAIR functions as a competing endogenous RNA to regulate HER2 expression by sponging miR-31-3p in gastric cancer." (PMID 28415631, 2017).
gastric cancer (continued). "Dioscin inhibited the expression of HOTAIR and the proliferation rate of gastric cancer cells, indicating that the antitumor effect of dioscin may partly depend on its down regulation of HOTAIR." (PMID 27751178, 2016). "Our previous study showed that HOTAIR could also function as a competing endogenous RNA by sponging miR-331-3p in gastric cancer." (PMID 27036039, 2016). "Here we showed that dioscin may inhibit the proliferation of gastric cancer through decreasing the expression level of HOTAIR." (PMID 27751178, 2016). "Plasma HOTAIR levels in gastric cancer patients are higher than health controls." (PMID 26788991, 2016). "Taken together, HOTAIR played an important role in the pathological process of gastric cancer." (PMID 27751178, 2016). "For example, the well-known lncRNA, HOTAIR, could function as a sponge of miR-331-3p to promote gastric cancer progression." (PMID 27285756, 2016). "Similarly as in gastric cancer, HOTAIR expression was found to be higher in castration-resistant prostate cancer cell lines than in normal prostate cells." (PMID 26978351, 2016). "The expression of HOTAIR is up regulated in gastric cancer and gastric cancer cell lines, dioscin inhibits the proliferation of three gastric cancer cell lines and the anti-tumor effect of dioscin may partly depend on the down regulation of HOTAIR." (PMID 27751178, 2016). "Moreover, decreased levels of HOTAIR expression resulted in significant increased expression of E-cadherin but decreased expression of N-cadherin and vimentin in gastric cancer cells." (PMID 26136075, 2015). "Also HOTAIR was shown to act as an endogenous sponge of miR-331-3p miRNA, thus abolishing repression of its target HER2, implicated in development of gastric cancer." (PMID 25954300, 2015). "In gastric cancer, HOTAIR overexpression has been correlated with advanced staging, lymph node metastasis, and poor overall survival, suggesting it may serve as a biomarker for poor prognosis." (PMID 26379360, 2015). "It has been demonstrated that knockdown of HOTAIR could reverse EMT process in gastric cancer cells." (PMID 25405331, 2015). "HOTAIR plays a pivotal role in the development of gastric cancer." (PMID 26172293, 2015). "In addition, miR34a expression was downregulated and negatively correlated with HOTAIR expression in gastric cancer tissues." (PMID 26136075, 2015). "Taken together, these results indicate that HOTAIR possesses metastasis-promoting activity and that its upregulation may facilitate the metastasis of gastric cancer cells." (PMID 26136075, 2015). "Moreover, HOTAIR inhibits miR-34a expression in prostate cancer, miR-331-3p expression in gastric cancer and miR-141 expression in renal carcinoma cells." (PMID 26183397, 2015). "HOTAIR, GCAT1 (gastric cancer-associated transcript 1), H19, and SUMO1P3 (small ubiquitin-like modifier SUMO 1 pseudogene 3) are the main lncRNAS reported as overexpressed in gastric carcinomas." (PMID 26448935, 2015). "HOTAIR overexpression represents a biomarker of poor prognosis in gastric cancer, and may confer malignant phenotype to tumor cells." (PMID 24775712, 2014). "In addition, HOTAIR:miR-331-3P coimmunoprecipitation with anti-Ago2 demonstrated a physical interaction in gastric cancer cells, providing further support for HOTAIR’s miRNA-sequestering activity." (PMID 24775712, 2014). "Recent studies reported that HOTAIR was upregulated in gastric cancer." (PMID 24775712, 2014). "Furthermore, HOTAIR overexpression promoted the proliferation, migration and invasion of gastric carcinoma cells, while HOTAIR depletion inhibited both cell invasion and cell viability, and induced growth arrest in vitro and in vivo." (PMID 24775712, 2014). "Furthermore, HOTAIR overexpression promoted the proliferation, migration and invasion of gastric carcinoma cells, while HOTAIR depletion inhibited cell invasion and cell viability, and induced growth arrest both in vitro and in vivo." (PMID 24775712, 2014).
gastric cancer (continued). "In the current study, we investigated the involvement of HOTAIR in human gastric cancer development and examined whether its expression would correlate with the aggressive behavior of gastric cancer." (PMID 24130837, 2013). "This might be due to the small number of patients in the current study, since forced expression of HOTAIR in an intestinal gastric cancer cell line (MKN74) gained the aggressive phenotype in vitro and in vivo." (PMID 24130837, 2013). "In addition, the gastric cancer cells with similar HOTAIR expression level (MKN-HOTAIR and shHOTAIR-3) formed similar numbers of colonies, indicating that anchorage-independent growth of gastric cancer cells was regulated in a HOTAIR-dependent manner." (PMID 24130837, 2013). "However, little is known about the expression and/or the function of HOTAIR in gastric carcinoma development." (PMID 24130837, 2013). "HULC, H19, HOTAIR, and GACAT2 (for “gastric cancer-associated transcript 2”) were found to be significantly increased in the plasma of gastric cancer (GC) patients compared to healthy individuals." (PMID 37190024, 2023). "We investigated the prognostic value of HOTAIR expression in gastric cancer (GC) and systematically delineate the expression in relation to Helicobacter pylori infection and preneoplastic changes." (PMID 35347094, 2022). "Moreover, the HOTAIR level acts as an oncogene in patients with gastric cancer." (PMID 36361470, 2022). "Many studies have highlighted the functional interaction between HOTAIR and different miRNAs in gastric cancer (GC)." (PMID 33540611, 2021). "Previous studies suggest that HOTAIR contributes to gastric cancer (GC) development, and the overexpression of HOTAIR predicts a poor prognosis." (PMID 26136075, 2015). "Moreover, ectopic overexpression of miR-331-3p or miR-124 expression could arrest gastric cancer proliferation, which was consistent with results of knockdown of HOTAIR expression in gastric cancer cells." (PMID 24775712, 2014). "However, the molecular mechanism of HOTAIR in gastric cancer is poorly understood." (PMID 25334066, 2014). "Studies of HOTAIR in gastric cancer (GC) have just begun, but its relevance has already been demonstrated." (PMID 25334066, 2014). "Lastly, the findings presented in this study have allowed us to conclude that HOTAIR overexpression represents an excellent biomarker of poor prognosis in gastric cancer, and may confer multiple properties required for tumor progression and metastatic phenotype." (PMID 24775712, 2014). "Scientists have identified HOTAIR overexpression as a marker that indicates tumor invasion and metastasis together with reduced clinical effectiveness in breast cancer and liver cancer and gastric cancer (GC) cases." (PMID 40959208, 2025). "Some typical "microRNA sponges" such as H19 30, PRKCA-AS1 31, HOTAIR 32 and XIST 33 have been involved in regulating tumor progression in nasopharyngeal carcinoma, uveal melanoma and gastric cancer." (PMID 38370382, 2024). "For example, HOTAIR and LINC00152 show high specificity in identifying colorectal and gastric cancers, respectively." (PMID 38615287, 2024). "In gastric cancer, HOTAIR regulates the expression of miR-34a through PRC2, thereby affecting the invasion and metastasis of gastric cancer." (PMID 37576402, 2023). "HOTAIR, through promoting Mex3b-dependent ubiquitination and degradation of RUNX3, suppresses Claudin1 expression to foster gastric cancer cell invasion and EMT." (PMID 36899853, 2023). "Mechanistically, HOTAIR complexes with Mex3b to ubiquitinate and degrade RUNX3 in gastric cancer cells, leading to increased cancer invasiveness." (PMID 36899853, 2023). "For example, HOTAIR can target miR-126 to activate CXCR4 and RhoA signaling pathways and promote the proliferation of gastric cancer cells." (PMID 35093153, 2022).
gastric cancer (continued). "Studies have shown that lncRNA HOTAIR upregulation in GC may promote human epidermal HER2 cell invasion by binding to miR-331-3p, thereby promoting gastric cancer cell invasion." (PMID 35240920, 2022). "Some identified oncogenic lncRNAs overexpressed in gastric cancerous tissue, such as H19, HOTAIR, and MALAT1, whereas others are expressed in the tissue from gastric carcinoma at a low level, such as LincRNA-p21, LINC00261, CTLSP4 and SPRY4-IT1." (PMID 36310592, 2022). "It has been reported that HOTAIR, ANRIL, GAPLINC, GHET1, H19, GAS5, and FENDRR, etc., play roles in the malignant progression of gastric cancer." (PMID 33744848, 2021). "Some of them are reported to promote the metastasis of gastric cancer, such as lncRNA UBE2CP3, HOTAIR and GMAN." (PMID 35127712, 2021). "HOTAIR knockdown had antitumor effects by suppressing CCND1 and CCND2 expression by stimulating miRNA‐206 in gastric cancer in vitro study." (PMID 33473276, 2021). "Multiple onco-lncRNAs, such as HOTAIR, CASC9, MRUL, UCA1, D63785, NEAT1 and HULC, are involved in ADR resistance in gastric cancer." (PMID 32192494, 2020). "Striking distinctions of HOTAIR, miR‐17‐5p, and PTEN expressions were observed between gastric cancer tissues and para‐carcinoma normal tissues (P < 0.05)." (PMID 30338929, 2019). "In a recent study, HOTAIR was also found to recruit PRC2 to catalyze H3K27 trimethylation to transcriptionally repress E-cadherin and promote EMT in gastric cancer." (PMID 31195674, 2019). "Among the studied gastric cancer cell lines (ie BGC‐823, MGC‐803, SGC‐7901, and MKN28), HOTAIR and miR‐175‐5p displayed the highest expressions within MKN28 (all P < 0.05)." (PMID 30338929, 2019). "Contrary to HOTAIR and miR‐17‐5p, PTEN expression within gastric cancer tissues achieved only half of that within para‐carcinoma tissues (P < 0.05)." (PMID 30338929, 2019). "Our previous studies have revealed that the expression pattern of several lncRNAs, such as HOTAIR, SPRY4-IT1, BANCR, and PVT1, is altered in human NSCLC and gastric cancer." (PMID 27713133, 2017). "In accordance with the previous studies, lncRNA H19 and lncRNA HOTAIR were up-regulated and LINC00261 was down-regulated in stomach cancer." (PMID 28484081, 2017). "Through the competitive ‘sequestration’ of miR-331-3p/miR-124, HOTAIR and erythroblastic leukemia viral oncogene homolog 2 (HER2) mRNA become a pair of ceRNAs in gastric cancer." (PMID 26788991, 2016). "The positive correlations of HOTAIR/HLA-G and lncRNA-BC032469/hTERT provide potential immunotherapy targets on gastric cancer." (PMID 26788991, 2016). "Along these same lines, cooperation between the lncRNA HOTAIR and miR-196a, both located within the HOXC cluster, has previously been described in gastric cancer, where both had prognostic value and the upregulation of both increased malignancy." (PMID 26436590, 2015). "Of the four gastric cancer cell lines investigated (MGC-803, SGC-7901, BGC-823, and AGS), BGC-823 expressed higher levels of HOTAIR (3.18-fold) than the normal gastric epithelium cell line (GES-1)." (PMID 24775712, 2014). "The present work provides the first evidence for a positive HOTAIR/HER2 correlation and the crosstalk between miR-331-3p, HOTAIR and HER2, shedding new light on the treatment of gastric cancer." (PMID 24775712, 2014). "Our results clearly revealed enhanced expression of HOTAIR in cancer tissues compared to non-cancerous tissues of the stomach and that the high level expression of this molecule was associated with lymph node metastasis, venous invasion and poor survival in the diffuse type of gastric cancer." (PMID 24130837, 2013). "Similarly, in gastric cancer, it contributes to OXP-resistance via the HOTAIR/miR-195-5p/ABCG2 axis, where the lncRNA HOTAIR acts as a ceRNA to sponge miR-195-5p, thereby upregulating ABCG2 expression and promoting OXP-resistance in cancer cells." (PMID 39401197, 2024).